UGT1A1 (UDP glucuronosyltransferase family 1 member A1)
Diseases named in the same sentence as UGT1A1 in open-access papers (continued):
Sharing a sentence is not in itself a finding about the gene and the disease.
tumor (continued). "This could improve tumour response in CRC cancer patients with various UGT1A1 genotypes, as well as minimising unnecessary adverse reactions such as severe neutropaenia." (PMID 19338662, 2009). "We then asked whether a genetic variation in UGT1A1 or SULT1A1 influenced specific tumor phenotypes." (PMID 16280036, 2005). "Furthermore, we observed that individuals with both high-activity SULT1A1 and high-activity UGT1A1 genotypes were more likely to have a lower tumor grade than those with other genotypes." (PMID 16280036, 2005). "The study suggested that UGT1A1-28 polymorphism could not be relied upon as a consistent predictor of both tumor response and progression-free survival (PFS) in CRC patients undergoing Irinotecan-based chemotherapy." (PMID 40432911, 2025). "Thus, treatment with irinotecan may be a better alternative for patients with UGT1A1 WT or when tumor progression is rapid." (PMID 32666389, 2020). "Therefore, UGT1A1 genotype and primary tumour location should have been included as stratification factors to avoid bias that could have influenced the results in survival or disease control rates." (PMID 30585257, 2019). "Furthermore, UGT1A1 gene did not reveal any significant association with studied tumor characteristics." (PMID 25648141, 2015). "The inhibition of UGT1A1 activity by bavachalcone might significantly affect the elimination of belinostat and then initiate the adverse effect when belinostat was coadministered with bavachalcone to treat tumor." (PMID 24829606, 2014). "Eight (57%) of the patients were men, median age was 63 (range 44–77), 10 (71%) had a high grade tumor by histologic examination, 8 (57%) patients were 6/6 TA repeats (i.e., negative for the UGT1A1*28 polymorphism, where a seventh TA sequence is present in the TATA sequence of the UGT1A1 promoter)." (PMID 22815703, 2012). "Results showed that four prognostic genes (ADH1B, ADH4, UGT1A1, and GPX3) exhibited significantly lower expression in tumor samples compared to normal samples." (PMID 41031088, 2025). "Specifically, FN1 (Log2 FC = 6.2), UGT1A1 (Log2 FC = 6.1), AGT (Log2 FC = 3.31), and COMT (Log2 FC = 2.4) were significantly upregulated in tumor tissues compared to normal tissues." (PMID 40564071, 2025). "Among the three subfamilies (UGT1A, 2A, and 2B) of the UGTs, UGT1A enzymes, particularly UGT1A1, have been shown to overexpress in tumor tissues and play a role in resistance to anticancer drugs." (PMID 37229486, 2023). "By utilizing certain specific substrates for UGTs, we initially demonstrated that catalytic activities of UGT1A, UGT1A1, UGT1A4, UGT1A9 and UGT2B7 were significantly decreased in the tumor tissues in HBV-positive HCC patients." (PMID 26010150, 2015). "Members of the ATP-binding cassette superfamily of proteins (ABCB1 and ABCG2) function to export irinotecan from tumour cells, while drug metabolism via the cytochrome P450 system (CYP3A4) or glucuronidation (UGT1A1) can also occur." (PMID 15655543, 2005). "Genotyping of UGT1A1 haplotypes was not performed, but evaluation of Trop 2 expression as a tumor biomarker was included." (PMID 39518062, 2024). "As the tumor progressed rapidly, genetic testing of tumor showed no mutation in BRCA1 and BRCA2 while UGT1AI*6, UGT1A1*28, UGT1A1-3156 gene polymorphism was detected." (PMID 36741732, 2022). "Neither hematologic toxicity (grade ≥ 3 in 52.9%, 30.0%, and 33.3%, respectively, of the 6/6, 6/7, and 7/7 genotype groups) nor tumor RR (41.2%, 33%, and 33%, respectively) were found to differ significantly by UGT1A1 genotype." (PMID 35200603, 2022). "Given the increasing incidence and mortality of HCC with the high HBV-infection background in China, we systematically analyzed the metabolic function, protein and gene expression levels of UGT1A, UGT1A1, UGT1A9, UGT1A4 and UGT2B7 in HBV-positive HCC tumor and the adjacent normal tissues." (PMID 26010150, 2015).
tumor (continued). "The results revealed that in the tumor human liver microsomes (HLMs), either Vmax (maximum reaction rate, Rmax for UGT1A1) or the clearance rates (Vmax/Km, Clint) of UGT1A, UGT1A1, UGT1A4, UGT1A9 and UGT2B7 were significant lower than those of in the adjacent normal HLMs." (PMID 26010150, 2015). "The statistical significance of the association between the interaction of high-activity SULT1A1 and UGT1A1 genotypes with low tumor grade, however, was no longer significant within the group of only Caucasian women (OR = 1.96, CI = 0.75–5.00, P = 0.19)." (PMID 16280036, 2005). "Furthermore, tumour response rates were not significantly different among UGT1A1 genotypes and TA7/TA7 patients tolerated the same number of IRI cycles and dosage compared to the other genotypes." (PMID 18594531, 2008).
cardiovascular disease (8 papers, 2013 to 2024). "We tested the hypothesis of whether the UGT1A1*28-linked SNP rs887829 and higher levels of bilirubin are associated with a lower risk of cardiovascular disease in our cohort." (PMID 37627608, 2023). "An inverse association between the homozygote UGT1A1*28 allele with higher serum bilirubin concentrations and the risk of cardiovascular disease has been reported in some studies, but not in other studies of adults." (PMID 37627608, 2023). "Serum bilirubin levels, which are determined by a complex interplay of various enzymes, including heme oxygenase-1 (HO-1) and uridine diphosphate–glucuronosyl transferase (UGT1A1), may be protective against progression of cardiovascular disease (CVD) in hemodialysis patients." (PMID 34573035, 2021).
genetic disorder (8 papers, 2014 to 2025). "GS is a benign genetic disorder characterized by elevated bilirubin levels, the primary cause of which is the presence of polymorphisms in UGT1A1 gene." (PMID 38766628, 2024). "Noteworthy, the ROR for PTs of UGT1A1 gene mutation is 4378.02 (396.92–48289.81) high, this may be one of the major reasons why the SOC signal of congenital, familial and genetic disorders is so significant." (PMID 38027003, 2023).
metabolic disease (7 papers, 2015 to 2024). A congenital disorder (due to inherited enzyme abnormality) or acquired (due to failure of a metabolically important organ) disorder resulting from an abnormal metabolic process. "Among the diseases caused by dysregulation of UGT1A1 activity, treatment of CN1, which is an inherited metabolic disease (IMD) caused by the complete loss of UGT1A1 activity, has always been a puzzling problem for health care providers." (PMID 34034810, 2021). "Crigle‐Najjar syndrome type 1 (CN1) is a rare metabolic disease characterized by the absence or decreased activity of UDP glucuronosyltransferase family 1 member A1 (UGT1A1), an enzyme required for glucuronidation of unconjugated bilirubin in the liver." (PMID 37206219, 2023). "The inhibition of UGT1A1 enzyme can make the bilirubin metabolism be metabolic disorders, and induce toxicity." (PMID 29887801, 2018).
infection (4 papers, 2004 to 2024). The state of being infected such as from the introduction of a foreign agent such as serum, vaccine, antigenic substance or organism. "This evidence suggested that bilirubin metabolism is impaired in mice after S. japonicum infection, consistent with the inhibition of hepatic UGT1A1 expression following infection." (PMID 38668242, 2024). "The mRNA expression of UGT1A1 in the liver of mice at 6, 8, and 10 weeks after infection was consistently lower than that in the control group (p < 0.0001)." (PMID 38668242, 2024). "Compared with that in the control group, the mRNA expression of PXR and CAR in the liver at 6, 8, and 10 weeks after infection was significantly lower, and the changing trend was the same as that of UGT1A1 (p < 0.0001, p < 0.0001)." (PMID 38668242, 2024). "In the current study, we noted that UGT1A1, ALB, and COX6A1 in the late-infection-stage PPI are associated with liver homeostasis." (PMID 39625960, 2024). "Moreover, UGT1A1 was noted to be downregulated in the late infection stage, suggesting that bilirubin accumulation occurred in the mouse liver, resulting in other adverse reactions or hepatotoxicity." (PMID 39625960, 2024).
adenocarcinoma (3 papers, 2022 to 2023). A common cancer characterized by the presence of malignant glandular cells. "The most common histology type was adenocarcinoma, and homo- or double-heterotype UGT1A1 statuses were observed in nine patients." (PMID 36670426, 2023).
colon (2 papers, 2020 to 2025). "Additionally, the detoxification function of UGT1A1 has been confirmed to be closely associated with the risk of digestive system tumors." (PMID 41031088, 2025).
UGT1A1 also shares sentences with these, for which no sentence is quoted: bladder cancer (11 papers); Crigler-Najjar syndrome type 2 (8); Insulin resistance (4); liver dysfunction (3); primary sclerosing cholangitis (3); acute liver failure (2); Alpha-thalassemia (2); Anorexia (2); Anxiety (2); hemochromatosis (2); hemoglobinopathy (2); intrahepatic cholangiocarcinoma (2); invasive breast carcinoma (2); liver cancer (2); Lynch syndrome (2); Sepsis (2); triple-negative breast carcinoma (2); acute myocardial infarction (1); adenoma (1); alcoholic liver diseases (1); alveolar rhabdomyosarcoma (1); anaphylaxis (1); atherosclerosis (1); autosomal recessive hereditary disease (1); biliary tract cancer (1); bilirubin metabolism disorder (1); CHARGE syndrome (1); cholecystolithiasis (1); Cholestatic liver disease (1); chronic myeloid leukemia (1).
A further 65 diseases each share a sentence with UGT1A1 in 1 paper.